TUB (TUB bipartite transcription factor)
Description:
Functions in signal transduction from heterotrimeric G protein-coupled receptors. Binds to membranes containing phosphatidylinositol 4,5-bisphosphate. Can bind DNA (in vitro). May contribute to the regulation of transcription in the nucleus. Could be involved in the hypothalamic regulation of body weight (By similarity). Contribute to stimulation of phagocytosis of apoptotic retinal pigment epithelium (RPE) cells and macrophages.
Synonyms: rd5; RDOB
Tractability: Small molecule: it has a high-quality binding pocket. Antibody: UniProt places it where antibodies can reach, with medium confidence; its Gene Ontology location is reachable by antibodies, with medium confidence; the Human Protein Atlas places it where antibodies can reach. PROTAC: ubiquitination databases record sites on it; its protein half-life has been measured.
Gene: Protein-coding gene on chromosome 11 (8,019,244 to 8,106,243, forward strand). Ensembl gene ENSG00000166402.
Subcellular location: Cytoplasm; Nucleus; Secreted; Cell membrane
Subcellular location (Human Protein Atlas): Basal body; Centriolar satellite; Plasma membrane; Vesicles
Gene Ontology:
Molecular function: G protein-coupled receptor binding; intraciliary transport particle A binding; protein-containing complex binding
Biological process: intraciliary transport; positive regulation of phagocytosis; protein localization to cilium
Cellular component: cilium; cytoplasm; nucleus; cytosol; extracellular region; plasma membrane
Genetic constraint (gnomAD): Loss-of-function variants: 31 observed, 55.52 expected, observed/expected ratio (o/e) 0.56, 90% interval 0.42 to 0.75. The upper end of that interval is the gene's LOEUF score, 0.75, which puts it in group 3 of 6, group 1 being the genes least tolerant of losing a copy. Missense variants: 655 observed, 690.83 expected, observed/expected ratio (o/e) 0.95, 90% interval 0.89 to 1.01. Synonymous variants: 292 observed, 266.32 expected, observed/expected ratio (o/e) 1.1, 90% interval 1 to 1.21.
Homologues: Orthologues: chimpanzee TUB (98% identical), rabbit TUB (96% identical), mouse Tub (95% identical), dog TUB (93% identical), rat Tub (93% identical), guinea pig TUB (93% identical), pig TUB (90% identical), macaque TUB (86% identical), zebrafish tub (74% identical), tropical clawed frog tub (66% identical). Paralogues in human: TULP3 (48% identical), TULP1 (48% identical), TULP2 (37% identical), TULP4 (24% identical), WDR35 (16% identical).
Diseases named in the same sentence as TUB in open-access papers:
TUB is named in the same sentence as 30 diseases in open-access papers, as found by Europe PMC text mining. Sharing a sentence is not in itself a finding about the gene and the disease. The quoted sentences say what the papers report.
Obesity (19 papers, 2008 to 2025). Accumulation of substantial excess body fat. "In humans, a mutation in TUB has been identified in siblings from a consanguineous family with early-onset obesity and retinal dystrophy." (PMID 40702736, 2025). "Till now, only one arRP-associated mutation in TUB for has been reported in the literature, in which a homozygous frameshift variant resulted in retinal dystrophy, hearing loss, and obesity in a consanguineous UK Caucasian family." (PMID 36650547, 2023). "For example, tubby mice—which exhibit a loss-of-function mutation in the TUB gene, the founding member of the Tubby family—manifest an obese phenotype, and homozygous mutation in TUB has been associated with early-onset obesity in humans." (PMID 37064917, 2023). "Given the limited number of human studies that have examined the association between TUB SNPs and obesity, unraveling the differences in common genetic variation across racial and ethnic groups is important." (PMID 33983957, 2021). "We show that candidate SNPs in the FTO and TUB genes are associated with obesity in African Americans and Hispanic/Latinos individuals respectively." (PMID 33983957, 2021). "A similar analysis in the H/L cohort identified the rs227383 SNP on chromosome 11 in TUB to be associated with obesity (OR 1.34; 95% CI: 1.04–1.71; P = 0.02)." (PMID 33983957, 2021). "We showed that rs8050136 (in FTO) in AAs and rs2272383 (in TUB) in H/Ls were associated with obesity." (PMID 33983957, 2021). "With improved understanding of the underlying pathophysiologic mechanisms by which TUB SNPs increase the risk of obesity will not only provide important insights into the obesity epidemic in the H/L population but also identify potentially therapeutic targets." (PMID 33983957, 2021). "Further validation and functional studies are needed to confirm our findings and to determine the underlying mechanisms by which FTO and TUB SNPs modulate susceptibility to obesity across racial and ethnic groups." (PMID 33983957, 2021). "In conclusion, our study confirms the association between common genetic variants in the FTO and TUB genes and increased risk for developing obesity in individuals of African and Hispanic descent respectively." (PMID 33983957, 2021). "TUB encodes a transcription factor predominantly expressed in neuronal cells and has been previously implicated in obesity." (PMID 32956375, 2020). "We find that a variant of the gene encoding the well-known transcription factor TUB, which has been previously implicated in obesity, is associated with familial ET." (PMID 32956375, 2020). "Rs4929949 is also located ∼500 kb downstream from the gene encoding TUB (Tubby protein homolog), which has been linked to body weight and obesity in mouse studies as well as early genetic studies, but remains unconfirmed in GWAS." (PMID 23967198, 2013). "In a previous study, we found that common variants of the TUB gene can influence body weight and contribute to obesity in diabetics." (PMID 18183286, 2008). "TUB was the first member of the Tubby gene family to be identified in obese mice, and splicing defects in the carboxyl-terminal intron of TUB lead to the maturity-associated obesity and delayed obesity associated with insulin resistance." (PMID 40282234, 2025). "A recessive mutation in the TUB gene leads to obesity, deafness, and retinal degeneration." (PMID 38785568, 2024). "Thus far, only one mutation in TUB for arRP have been reported in the literature, in which a homozygous frameshift variant resulted in retinal dystrophy, hearing loss, and obesity in a consanguineous UK Caucasian family." (PMID 36650547, 2023). "A TUB frameshift mutation in three siblings was associated with retinal dystrophy and obesity." (PMID 35893067, 2022).
Obesity (continued). "After adjusting for age and sex, we found that rs8050136 in FTO (odds ratio [OR] 1.40, 95% confidence interval [CI] 1.1–1.8; P = 0.01) among African Americans and rs2272383 in TUB (OR 1.34, 95% CI 1.04–1.71; P = 0.02) among Hispanic/Latinos were associated with obesity." (PMID 33983957, 2021). "In contrast to known forms of retinal dystrophy, including those caused by mutations in the tubby-like protein TULP-1, loss of function of TUB in the proband and two affected family members was associated with early-onset obesity, consistent with an additional role for TUB in energy homeostasis." (PMID 24375934, 2014). "However, the observed association is more likely to be due to the strong linkage disequilibrium of rs1528133 with SNPs in the highly conserved 3′ end of the TUB gene, since the mutations in this part of TUB are known to cause obesity in tubby mice." (PMID 18183286, 2008). "However, only mild obesity was observed in a patient carrying a different TUB mutation." (PMID 40702736, 2025). "Heterozygous carriage of recessive mutations was observed in the ADCY3 (adenylate cyclase 3), CEP290 (centrosomal protein), and TUB (Tubby-like protein) genes, which are involved in obesity pathogenesis." (PMID 40149731, 2025). "Therapeutic targeting of the thermogenesis and orexigenic or anorexigenic pathways that are regulated by the FTO and TUB genes respectively has important clinical implications for the obesity epidemic especially in ethnic minorities." (PMID 33983957, 2021). "Mammalian TUB gene is related with the occurrence of TUB protein, which belongs to the tubby-like proteins (TULPs), related with maturity-onset obesity formation." (PMID 34681728, 2021). "Rare familial monogenic obesity syndromes have been informative in elucidating underpinnings of obesity, demonstrating roles for genes such as SIM1 and TUB in obesity." (PMID 30563851, 2018). "Altogether, all of this implies the importance of further investigation into the TUB role in human obesity." (PMID 18183286, 2008). "Mutations in the TUB gene can lead to obesity, and TULP3 is the family member most closely related to TUB, so we speculate that it may also have something to do with obesity formation." (PMID 40282234, 2025). "Finally, a prior study established a clear relationship between TUB and obesity by examining its expression in the hypothalamus and adipose tissue." (PMID 38674329, 2024). "The TUB gene was discovered in the 1990’s as a relevant marker for obesity in mice." (PMID 33983957, 2021). "The exact mechanism linking the loss of the TUB function in the tubby mice, and their adult-onset obesity is still not clear." (PMID 18183286, 2008). "In addition, it showed how TUB could be a potential biomarker or therapeutic target for obesity-related conditions." (PMID 38674329, 2024). "Previous studies have shown that TUB and TULP genes in mammalian involve in obesity, neural development, and retinal degeneration." (PMID 23228091, 2012).
retinal degeneration (4 papers, 2012 to 2024). Degeneration of the retina. "Abundantly expressed in the retina, brain, and cochlea with dual localization to the plasma membrane and nucleus, TUB has been implicated in energy balance, retinal degeneration, and neuronal regulation in mice." (PMID 36650547, 2023). "TUB codes for the tubby bipartite transcription factor and has been implicated in maturity-onset obesity, insulin resistance, retinal degeneration, and neurosensory hearing loss in mice, with TUB mutations associated with each of these phenotypes when inherited in an autosomal recessive mode." (PMID 32956375, 2020).
Retinal dystrophy (4 papers, 2014 to 2023). Retinal dystrophy is an abnormality of the retina associated with a hereditary process. "By exome sequencing in a cohort of molecularly unsolved individuals with IRD, we identified a homozygous splice site variant affecting the transcript processing of TUB, encoding the first member of the Tubby family of bipartite transcription factors, in a sporadic case with retinal dystrophy." (PMID 36498982, 2022).
Insulin resistance (3 papers, 2008 to 2025). Increased resistance towards insulin, that is, diminished effectiveness of insulin in reducing blood glucose levels. "Mutations in TUB cause late-onset obesity, insulin-resistance and neurosensory deficits in mice." (PMID 18183286, 2008).
ciliopathy (2 papers, 2014 to 2015). A genetic disorder of the cellular cilia or the cilia anchoring structures, the basal bodies, or of ciliary function. "We also observed that knockdown of ciliopathy genes ALMS1, BUBR1 [BUB1B], IFT80, NPHP1, NPHP8 [RPGRIP1L], TCTN2, TMEM216 and TUB retarded neuronal migration." (PMID 26206566, 2015).
mastitis (2 papers, 2021 to 2022). Inflammation of breast tissue during lactation or postpartum due to an obstructed duct or infection. "In the cell model of bovine S. aureus mastitis, the S. aureus adhesion to epithelial cells can be mediated by lncRNAs TUB and H19, and the NF-κB/NLRP3 inflammasome pathway is regulated by the lncRNA XIST." (PMID 34895356, 2021).
viral infection (2 papers, 2012 to 2025). "We selected 16 candidate reference genes, some of which were commonly used as normalisation factors in qRT–PCR analysis, such as GAPDH, 18S, EF1α, ACT and TUB, and other genes showed a high expression stability in plant species under viral infection or other experimental settings." (PMID 23029521, 2012). "Conversely, APR, TUB, SAMD, ACT and GAPDH showed relatively low expression stability in leaf tissues of N. benthamiana during viral infections." (PMID 23029521, 2012). "It is worth noting that genes relating to innate immune response to viral infection (e.g., DHX58, MX1, IFITM-like), cell structure integrity (e.g., ANGPTL3, ANGPTL4, ELFN2, COL5A3) and transcription factors (e.g., TUB) remained upregulated throughout the acute phase of infection (1–6 dpi)." (PMID 40758745, 2025).
essential tremor (1 paper, 2020). A relatively common disorder characterized by a fairly specific pattern of tremors which are most prominent in the upper extremities and neck, inducing titubations of the head. "We further show that mutations of the TUB gene are enriched in a cohort of essential tremor patients." (PMID 32956375, 2020).
hearing loss (1 paper, 2020). "An additional five genes have not previously been associated with human hearing loss but are known to cause hearing loss or cochlear development when mutated in mice: SYNJ2, RPGRIP1L, BAIAP2L2, TUB, and RBL2." (PMID 32986727, 2020).
hypothyroidism (1 paper, 2020). Abnormally low levels of thyroid hormone. "TUB expression is lower in rats with hypothyroidism, and T3 treatment of cultured neuronal cells increased TUB expression significantly." (PMID 32956375, 2020). "Their results indicate that in animals born with congenital hypothyroidism, the initiation of T3/T4 treatment in adulthood induces a low level of TUB expression; however, this effect is seen only in the Purkinje cells of the cerebellum, and not in other regions of the brain." (PMID 32956375, 2020).
lung adenocarcinoma (1 paper, 2017). A carcinoma that arises from the lung and is characterized by the presence of malignant glandular epithelial cells. "According to this data, LMN (lamin), VIM (vimentin), TUB (tubulin), and ACT (actin) detected with the help of aptamers LC-18, LC-17, and LC-24 are involved in cancer progression and could act as lung adenocarcinoma biomarkers." (PMID 29137182, 2017).
nematode infection (1 paper, 2016). "Many TF families such as TUB, TCP, SET, SBP, PHD, and Orphans have not been reported in the regulation of tomato leaf mold disease resistance, but some of these TFs have been reported in grapevine (Vitis amurensis) against downy mildew and in ramie against root-lesion nematode infection." (PMID 28105042, 2016).
Tremor (1 paper, 2020). An unintentional, oscillating to-and-fro muscle movement about a joint axis. "Moreover, the TUB protein modulates a broad spectrum of pathways, including key pathways relevant for tremor phenotype such as those involved in dopaminergic and cholinergic synaptic transmission, as well as axonal guidance." (PMID 32956375, 2020).
Usher syndrome type 3 (1 paper, 2024). A syndrome characterized by postlingual progressive hearing loss, abnormalities in the vestibular system, and onset of retinitis pigmentosa symptoms usually by the second decade of life. "However, bi-allelic variants in CLRN1, LSS, and TUB have been associated with AR Usher syndrome type 3, congenital cataract, or RP, respecitvely." (PMID 38785568, 2024).
tumor (5 papers, 2012 to 2025). "Additionally, NAD+ supplements can potentiate tumor-killing function by rescuing defective TUB-mediated NAMPT transcription in tumor-infiltrated T cells." (PMID 40861448, 2025). "Moreover, TUB low expression in circulating tumor cells inversely influenced patients’ OS as independent prognostic factors." (PMID 37752559, 2023). "NAD+ supplementation may promote tumor-killing by tumor-infiltrated T cells after anti-PD1 immune checkpoint inhibitor treatment or adoptive chimeric antigen receptor (CAR) T cells through rescuing defective TUB-mediated NAMPT transcription." (PMID 35801078, 2022). "Results demonstrated an invariably unmethylated (WNT10B) or methylated (TUB, ALOX12B, SLC6A11) status of the normal samples (data not shown) as compared to the variable levels of methylation observed in tumor cells." (PMID 22950745, 2012).
infection (3 papers, 2015 to 2025). The state of being infected such as from the introduction of a foreign agent such as serum, vaccine, antigenic substance or organism. "All the samples showed presence of TUB band thereby suggesting infection with Mycobacterium tuberculosis complex." (PMID 27099794, 2016). "geNorm analysis of T. leucotreta virus-infected samples at 25°C for 24, 48 and 72 hours post-infection selected ACT, AK, EF1 and TUB genes for normalization." (PMID 26030743, 2015).
genetic disease (1 paper, 2023). "Considering loss of function is a common mechanism of genetic disease, this homozygous variant coincidently resides on the last but one base of exon 11 of the TUB gene, which is classified as a type II splice variant." (PMID 36650547, 2023).
TUB also shares sentences with these, for which no sentence is quoted: cancer (3 papers); Aortic dissection (2); autosomal recessive retinitis pigmentosa (1); Bardet-Biedl syndrome (1); congenital hypothyroidism (1); deafness (1); lung carcinoma (1); obesity syndromes (1); pulmonary TB (1); retinal ciliopathy (1); syndromic (1); tuberculosis (1); type-2 diabetes (1).